TWIST2 (twist family bHLH transcription factor 2)
Diseases named in the same sentence as TWIST2 in open-access papers (continued):
Sharing a sentence is not in itself a finding about the gene and the disease.
tumor (continued). "In order to better understand the relationship between tumor budding, methylation and protein expression of TWIST1 and TWIST2, tumor budding status was divided into low (≤10 buds/10HPFs on average) and high (>10 buds/10 HPFs on average)." (PMID 25528769, 2015). "In this study, we investigated the possible link between TWIST1 and TWIST2 methylation in tumor epithelium and tumor stroma, the relationship with TWIST1 and TWIST2 protein expression and a possible role for these genes in promoting a tumor budding phenotype." (PMID 25528769, 2015). "Firstly, we show that TWIST1 and TWIST2 protein expression are found nearly exclusively in the tumor stroma." (PMID 25528769, 2015). "TWIST1 and TWIST2 promoter methylation and protein expression were investigated in six cell lines and further correlated with tumor budding in patient cohort 1 (n = 185)." (PMID 25528769, 2015). "Here we again observe extensive TWIST1 and TWIST2 staining in stromal cells within the main tumor body." (PMID 25528769, 2015). "Here, we found that TWIST2 was overexpressed in CRC tumor tissues compared with adjacent normal tissues." (PMID 24171926, 2013). "Twist2 promoted the survival of tumor cells through the PI-3K-Akt pathway, resulting in anti-apoptotic effects induced by tumor hypoxia." (PMID 23946798, 2013). "These properties support the notion that TWIST2 repression contributes to the tumor metastasis suppressive effects of miR-138." (PMID 24171926, 2013). "Closer observation of the immunoreactivity for Twist2 and HIF-1α revealed the co-expression of Twist2 with HIF-1α in the tumor cells (r=0.451, P<0.05)." (PMID 23946798, 2013). "Most cells with cytoplasmic Twist2 mostly showed E-cadherin on cell membrane, which is similar to the cancer cells at tumor center or metastases in vivo." (PMID 23133563, 2012). "Twist2 expression is upregulated significantly with tumor metastasis, especially distant lymph nodes metastasis (100%, 31 in 31)." (PMID 23133563, 2012). "In cells of the tumor center and lymph metastases, cytoplasmic expression of Twist2 correlated with an epithelial morphology and normal E-cadherin expression." (PMID 23133563, 2012). "In support of the transient EMT model, we have found differences between cells of the invasion front and cells of the tumor center in respect to both the subcellular localization of Twist2 and expression of E-cadherin." (PMID 23133563, 2012). "Twist2 (Dermo1) has been shown to mediate the epithelial-mesenchymal transition (EMT) to promote tumor invasion and even metastasis." (PMID 23133563, 2012). "When the tumor invasion front (IF) was compared with the tumor center (TC), a correlation can now be detected between the sub-cellular location of Twist2 and E-cadherin expression." (PMID 23133563, 2012). "Cytoplasmic Twist2 was associated with tumor histological type, the TNM clinical stage and tumor metastasis." (PMID 23133563, 2012). "TWIST2 has tumor-suppressive functions, which is in contrast to the oncogenic role of TWIST1." (PMID 39941895, 2025). "We identified CD36, MMP1, TGFBR3, TWIST2, ITGB1, and FGF19 as associated with poorer outcomes: CD36 enhances tumour stemness and growth, MMP1 facilitates metastasis, TGFBR3 and TWIST2 promote EMT and invasion, ITGB1 supports cell adhesion and survival, and FGF19 drives proliferation." (PMID 41007296, 2025). "The tumor tissues were used to detect the expression levels of TWIST2, E-cadherin, and vimentin." (PMID 36111260, 2022). "Moreover, Twist2 had been showed to accelerate tumor progression, which was regarded as a poor diagnosis of HCC, therefore, we tried to detect the expressions of Twist2 in HCC patients." (PMID 36262967, 2022). "Interestingly, western blot assay showed that the protein levels of Twist2 were significantly elevated in human HCC tumor tissues." (PMID 36262967, 2022).
tumor (continued). "Twist1 overexpression can induce tumor cell metastasis, whereas Twist2 is involved in the tumor growth stage; these two proteins have different functions in different tumor types The bHLH domain can specifically bind to the E-box domain on DNA to play a regulatory role." (PMID 33397409, 2021). "Furthermore, with analysis by a real-time qPCR, key transcriptional factors of the EMT such as Snail1, Snail2, Twist1, Twist2, Zeb1, and Zeb2, were found to be markedly expressed in Tg-6m tumor cells when normalized to Tg-3m tumor cells." (PMID 28419107, 2017). "For example, TWIST2 was reported to inhibit tumor formation in certain types of cancer." (PMID 29156759, 2017). "In CRC, the expression of TWIST1 and TWIST2 is generally restricted to the tumor stroma." (PMID 29258163, 2017). "Hypermethylation of TWIST1 and TWIST2 promoters in the tumor stroma may represent an alternative mechanism for regulation of TWIST1." (PMID 29258163, 2017). "Prominent stromal cell staining for TWIST1 and TWIST2 could be noted with only very infrequent expression within tumor epithelia." (PMID 25528769, 2015). "In accordance with our results of a possible inverse relationship between methylation and tumor budding phenotype, we observe a significant hypermethylation of TWIST1 and TWIST2 in correlation with low-grade budding and a hypomethylation of TWIST1 and TWIST2 in the high-grade budding tumor." (PMID 25528769, 2015). "In order to determine whether the hypermethylation of TWIST1 and TWIST2 as a mechanism for TWIST1 and TWIST2 down-regulation is restricted to tumor, we included analysis of 10 normal colonic tissues." (PMID 25528769, 2015). "Moreover, nuclear expression of MACC1, TWIST1, and TWIST2 was upregulated in GC tissues compared with matched adjacent non-tumorous tissues (p < 0.05)." (PMID 25895023, 2015). "We observed lack of correlation between hypermethylation and protein expression in normal colorectal mucosa may suggest that hypermethylation as a regulatory mechanism of TWIST1 and TWIST2 may be restricted to the tumor microenvironment." (PMID 25528769, 2015). "In addition, we found that the nuclear expression of MACC1, TWIST1, and TWIST2 proteins was significantly higher in the tumor tissues of VM-positive GC patients than in their matched adjacent non-tumor tissues (p = 0.045, p = 0.015, and p = 0.007)." (PMID 25895023, 2015). "TWIST1 and TWIST2 CpG methylation was correlated to protein expression and tumor budding status." (PMID 25528769, 2015). "And we speculate that miR-138 may function as a tumor metastasis inhibitor through the inhibition of CRC EMT by targeting TWIST2." (PMID 24171926, 2013). "Twist2 was only detectable in the cytoplasm of tumor cells at TC and the lymph metastases (LM)." (PMID 23133563, 2012). "Disseminating tumor cells at IF with nuclear Twist2 completely lost E-cadherin." (PMID 23133563, 2012). "Neither tumor location nor metastasis stage was associated with TWIST1 or TWIST2 expressions." (PMID 29156759, 2017). "TWIST2 may act as a tumor repressor by activating known tumor-suppressor genes." (PMID 29156759, 2017). "Twist2, while less well known than Twist1, plays essential roles in strengthening EMT programs and helping tumor cells survive." (PMID 41596524, 2026). "Collectively, these finding support a tumor suppressor role for both FAM107A and TWIST2 in PCa, with their methylation statuses serving as potential prognostic biomarkers." (PMID 41008642, 2025). "Freshly isolated cells were additionally characterized for specific mRNA expression of tumor (GPC3, SPINK1, SPP1, KPNA2) and fibroblast (COL1A2, TWIST2, FGF7) marker genes using RT–qPCR." (PMID 36077764, 2022). "CAF-mediated EMT, which is strongly correlated with the expression of AXL, TWIST2 and ADAM12 from the IMS, can result in biomechanical and biochemical changes that facilitate tumor immune escape, invasion, and metastasis." (PMID 33542239, 2021).
tumor (continued). "In the next step, expression level of stemness relatedgenes (OCT4, SOX2, KLF4, c-MYC and NANOG) and EMTtranscription factors (CDH1, CDH2, SNAIL1, TWIST1,TWIST2 and ZEB1) were evaluated in all tumor samples andmammospheres." (PMID 31376329, 2020). "The aim of this study was to analyze the expression of SNAIL, SLUG, TWIST1, TWIST2, ZEB1, and ZEB 2 in primary tumor and the correlation with morphological and clinical characteristics of EC." (PMID 33457409, 2020). "Hypoxia also promotes tumor metastasis by translational regulation of various proteins important in various phases of this process including EMT such as SNAIL1, SNAIL2, TWIST1, TWIST2, TGF-β, Wnt, and Notch." (PMID 32973493, 2020). "It is well known that SNAI1, SNAI2, ZEB1, ZEB2, TWIST1 and TWIST2 are key transcription factors involved in EMT in various types of cancers, and they contribute to enhanced tumour cell migration, invasion and metastasis capacities." (PMID 32488136, 2020). "The signals from primary tumor associated stroma such as TGF-β1 may trigger changes in cytoskeleton reorganization and lead to the activation of nuclear transcription factors, ZEB1, TWIST1 and TWIST2, which, once activated, implement EMT program and promote invasiveness." (PMID 29337896, 2018). "The frequent hypermethylation of Twist2 in human AML resulted in the inactivation of Twist2 and subsequent tumor growth." (PMID 29685144, 2018). "Thirdly, we performed laser capture microdissection to dissect out tumor epithelium from tumor stroma in regions previously stained for TWIST1 and TWIST2 protein." (PMID 25528769, 2015). "Twist2 is also considered to be an inducer of epithelial-mesenchymal transition (EMT), a well-known process involved in embryogenesis, tumor invasion, metastasis and drug resistance." (PMID 24944676, 2014). "However, the biological function of Twist2 in tumor has remained mostly unknown." (PMID 24244294, 2013). "Twist2 also affects critical signaling pathways like NF-κB and STAT3, which help create conditions in the TME that suppress the immune system and make it harder for the immune system to find and kill the tumor." (PMID 41596524, 2026). "Notably, the transcription factors TWIST2 and ZEB1—key drivers of EMT and tumor invasiveness—were significantly downregulated in SET-type tumors." (PMID 41155518, 2025). "Additionally, in cases with a poor prognosis, HIF1A-driven pathways, such as PI3K/AKT, TNF-α, and Wnt, promote tumour proliferation and survival by metabolic reprogramming, as well as upregulation of metastasis-promoting genes such as MMP1, TWIST2, and ITGB1." (PMID 41007296, 2025). "The animals were sacrificed, and the tumor tissue from stressed animals exhibited increased mRNA expression of the EMT-related genes Twist1, Twist2, Zeb1, Zeb2, Slug, and PLAGL2 and increased protein expression of PLAGL2, Ki67 (a proliferation marker), N-cadherin, and Vimentin." (PMID 38689092, 2024). "TWIST2 and SNAI1 are key regulators of tumor epithelial mesenchymalization." (PMID 37091977, 2023). "Moreover, the protein levels of Twist2 were negatively correlated with miR-1236-3p in HCC patients with metastasis and larger tumor size ( ≥5 cm, n = 35)." (PMID 36262967, 2022). "Our results suggest that the pro-tumor effects of TWIST1 and, to some degree, TWIST2 come from the tumor stroma and that this expression may be regulated at least in part by promoter hypermethylation." (PMID 25528769, 2015). "For instance, immunohistochemical expression of TWIST1 and TWIST2, known activators of EMT, was significantly positively correlated with a tumor-budding phenotype (both low-grade and high-grade budding), yet their expression was virtually restricted to stromal cells in the tumor microenvironment." (PMID 25806371, 2015). "Additionally we found significantly higher levels of Twist2 in the CD24+ cells, a transcription factor that enhances tumor invasion by promoting an epithelial-mesenchymal transition." (PMID 26040280, 2015).
tumor (continued). "SNAI2 (alias SLUG) and TWIST2, two key regulators involved in neural crest development and epithelial-mesenchymal transition (EMT), are also highly expressed in this group; these proteins are known to contribute heavily to cell motility and tumor metastasis." (PMID 20178649, 2010). "We studied a retrospective cohort of 160 consecutive surgically treated NSCLC patients with available frozen tumor samples for expression of EMT markers (CDH1, CTNNB1, CDH2, and VIMENTIN), inducers (TGFB1, c‐MET, and CAIX), and transcription factors (EMT‐TF:SNAI1, SNAI2, ZEB1, TWIST1, and TWIST2)." (PMID 29845746, 2018). "Twist1 and Twist2, as the main EMT-mediated process regulators, express high structural homology, and gene deletion tests have proved that two proteins share some similar effects and functions, such as their role in tumor progression and metastasis and their regulation of hematological malignancies." (PMID 26842802, 2016). "In addition, Twist2 protein levels in patients with metastasis and larger tumor size ( ≥5 cm, n = 35) were obviously higher than those patients with nonmetastasis and smaller tumor size (<5 cm, n = 21)." (PMID 36262967, 2022). "Bulk RNA-seq analysis of tumor ECs derived from three human patients with GBM confirmed specific knockdown of Twist1, but not Twist2, and identified about 400 differentially expressed genes in Twist1-knockdown ECs." (PMID 38416830, 2024). "Presumably, the most favorable (possibly default) state for the tumor is one in which TWIST1 and TWIST2 are not prevented from being expressed, thus allowing these genes to exert their functions and facilitating and progression." (PMID 25528769, 2015). "In contrast, the high-grade budding tumor showed considerable stromal cell staining of TWIST1 and TWIST2 while the low-grade budding cancers had a mostly negative stroma." (PMID 25528769, 2015).
cancer (51 papers, 2012 to 2025). A tumor composed of atypical neoplastic, often pleomorphic cells that invade other tissues. "In the present study, Twist2 expression was found to differ between human ovarian cisplatin-sensitive cancer cell line, OV2008, and the resistant variant, C13K cells." (PMID 24944676, 2014). "In contrast, transiently expressed Twist2 was strongly detected in nuclei of cancer cells with loss of E-cadherin." (PMID 23133563, 2012). "Considering the similarity and overlap of functions between the two Twist proteins in development and cancer, we hypothesized that an association existed between Twist2 and HIF-1α." (PMID 23946798, 2013). "In addition, Twist2 dysfunctions are associated with human pathological conditions characterized by oxidative stress-induced neuronal death, supporting its potential role as therapeutical target for cancer and neurological diseases." (PMID 37048129, 2023). "One study revealed that the knockdown of the Twist2 gene suppressed the expression of ITGA6 and CD44, which are involved in the migration and invasion of cancer cells and are associated with the ECM–receptor interaction pathway." (PMID 38254353, 2024). "Together with YAP1 several EMT-TFs (ZEB1, ZEB2, TWIST2) are upregulated in cancer cells after contact with fibroblasts." (PMID 36936987, 2023). "From a clinical point of view, Twist2 is upregulated in a variety of cancers, including glioma and neuroblastoma." (PMID 37048129, 2023). "TWIST2 can suppress the expression of FGF21 to activate the AMPK/mTOR signalling pathway which inhibits the progression of various cancers." (PMID 36118870, 2022). "The binding of TWIST2 to vascular endothelial cadherin (VE-cadherin) promoted vasculogenic mimicry (VM) formation in cancer cells." (PMID 35615155, 2022). "TWIST2 is a well-known metastatic trigger in various human cancer types, which is frequently overexpressed in cancer tissues and correlated with poor prognosis." (PMID 33949284, 2021). "These genes encode for proteins with well-known roles in cancer progression and normal stem cell maintenance (KIT), angiogenesis (SERPINE), and epithelial-mesenchymal transition (TWIST1, TWIST2, and ZEB2)." (PMID 31013771, 2019). "FLG interacts with MCL1, USP1, C21orf59, MAK, and KIR3DS1 and mucin interacts with ERBB3, SNAI1, TWIST1, TWIST2, and CDH2, all of which, IPA predicted to be associated with cancer." (PMID 31058088, 2019). "TWIST1 and TWIST2 expression in stroma were significantly positively correlated in low-grade (r = 0.41) and to a lesser extent in high-grade (r = 0.26) budding cancers." (PMID 25528769, 2015). "TWIST1 and TWIST2 share many functions, such as their regulation of hematological malignancies and their role in cancer progression and metastasis." (PMID 25895023, 2015). "Upregulation of Twist2 expression has been detected in a wide range of human cancers and Twist2 has already been shown to be a significant molecule in specific solid tumors." (PMID 24944676, 2014). "Twist2-driven EMT is critical in cancer progression and is able to markedly reduce E-cadherin expression." (PMID 23946798, 2013). "Twist2, also known as Dermo1, is from the basic helix-loop-helix transcription factor family and has been demonstrated to be essential in mediating cancer metastasis." (PMID 23946798, 2013). "Subcellular fraction analysis and immunofluorescent staining showed that stably expressed Twist2 was located in cytoplasm of the cancer cells." (PMID 23133563, 2012). "When cancer cells move to their new homing sites, Twist2 redistributes to the cytoplasm with E-cadherin re-expression, thus carcinoma cells revert into a noninvasive state in the absence of ongoing exposure to the micro-environmental signals." (PMID 23133563, 2012).